IDH2 (isocitrate dehydrogenase (NADP(+)) 2)
Diseases named in the same sentence as IDH2 in open-access papers (continued):
Sharing a sentence is not in itself a finding about the gene and the disease.
glioma (continued). "miR-183 has been reported to downregulate the enzyme isocitrate dehydrogenase 2 (IDH2) of the Krebs cycle in gliomas." (PMID 30116406, 2018). "The discovery of mutations in the isocitrate dehydrogenase genes 1 and 2 (IDH1, IDH2) in 2008 was a major breakthrough towards molecular biomarker-driven diagnosis of adult gliomas." (PMID 29098416, 2018). "While IDH1 mutations are more common in gliomas (80%) and AML (20%), IDH2 mutations occur more frequently in AML (20%) and cholangiosarcomas (20%)." (PMID 30405699, 2018). "Mutations in genes involved in important metabolic pathways, such as isocitrate dehydrogenase 1 and 2 (IDH1/IDH2), are important cancer drivers (e.g., gliomas and leukemias)." (PMID 30170631, 2018). "The most common mutations are IDH1 R132 and IDH2 R172, comprising roughly 90% of IDH mutations; the former is noted in more than 70% of grade 2/3 gliomas and in GBMs that progressed from these lower-grade tumors." (PMID 29899215, 2018). "Previous studies demonstrated that IDH1 mutations frequently occurred in grade II and III gliomas and secondary GBM glioblastoma, but rarely in primary GBM; whereas IDH2 mutations occur in fewer than 3% of glial tumors." (PMID 30061525, 2018). "Later in 2009, it was found in grade II and III gliomas and for the first time in an acute myeloid leukemia (AML) patient followed by other patients with IDH2 mutations." (PMID 29439493, 2018). "Frequently, in low-grade gliomas, single amino acid substitution mutations for an arginine residue in the active site of IDH1 and IDH2 evoked production of a new metabolite, 2-hydroxyglutarate (2-HG)." (PMID 29257069, 2017). "The discovery of IDH1 mutations in human glioma and the recent clinical findings in IDH1- and IDH2-mutant acute myeloid leukemia patients highlights the potential clinical utility of brain-penetrant IDH1 mutant-selective compounds." (PMID 29062039, 2017). "Somatic mutations in isocitrate dehydrogenase 1 (IDH1) and isocitrate dehydrogenase 2 (IDH2) have been detected in secondary glioblastomas, gliomas and acute myeloid leukemia (AML)." (PMID 28410203, 2017). "It was also found that many of the grade II/III gliomas and secondary GBMs that are IDH1 wild type had mutations at IDH2 R172." (PMID 28785398, 2017). "Hotspot mutations in IDH1 and, less frequently, IDH2 occur in 80% of WHO grade II-III and secondary WHO grade IV gliomas and are ancestral events in the formation of these neoplasms." (PMID 28467784, 2017). "Both IDH1 and IDH2 mutations were identified in ∼15% of gliomas, which were predominantly seen in grade II-III gliomas and secondary glioblastomas." (PMID 29290954, 2017). "Altogether, 80–90% of adult grade II/III gliomas and secondary GBMs harbor mutations at either R132 of IDH1 or R172 of IDH2." (PMID 28785398, 2017). "In this report, we compared the clinical and molecular characteristics of glioma patients harboring IDH1 and IDH2 mutations." (PMID 27245697, 2016). "Future work should focus on the potential of therapeutically targeting compensatory metabolic pathways in IDH2-mutant gliomas." (PMID 27245697, 2016). "For example, IDH1 mutations are predominant in gliomas, chondrosarcoma, and cholangiocarcinoma, whereas IDH1 mutations and IDH2 mutations are equally common in AML." (PMID 27245697, 2016). "Although knowledge of tumor subtype has clinical utility, the best prognostic indicator for patients with glial tumors is the mutational status of IDH1 and IDH2." (PMID 27923049, 2016). "In certain cancers especially glioma, mutations of the cytosolic (IDH1) or mitochondrial (IDH2) enzymes create a novel function in which they can further convert α-ketoglutarate to 2-hydroxyglutarate (2-HG)." (PMID 27358718, 2016). "Most grade II/III gliomas and secondary GBMs carry mutations in one of isocitrate dehydrogenase genes IDH1 or IDH2." (PMID 27693047, 2016).
glioma (continued). "Mutations in isocitrate dehydrogenase 1 (IDH1) and isocitrate dehydrogenase 2 (IDH2) are frequent in low-grade gliomas and secondary glioblastomas (sGBM)." (PMID 27245697, 2016). "The objective of this study was to provide insight into the differences between IDH1 and IDH2 mutant gliomas." (PMID 27245697, 2016). "Among 811 gliomas in our cohort, 448 cases (55.2 %) harbored an IDH1 mutation, 18 cases (2.2 %) harbored an IDH2 mutation and 345 cases (42.6 %) harbored an IDH1/2 wild-type." (PMID 27245697, 2016). "This group displays rare Tert promoter mutations (10 %); however, IDH1 and IDH2 mutations (75 %) as well as ATXR mutations (70 %) are common, which is also correlated with the high prevalence of ALT (63 %) in these gliomas." (PMID 26846696, 2016). "IDH1/2 mutations identified thus far are heterozygous and produce single amino acid substitutions either at arginine 132 (R132) in IDH1 or arginine 172 (R172) in IDH2 in glioma and leukemia, or at arginine 140 (R140) in IDH2 in AML." (PMID 27548812, 2016). "Mutations in the IDH1 or IDH2 genes are found in the majority of adult diffuse grade II and grade III gliomas and are considered as the earliest oncogenic event in these tumors." (PMID 27036230, 2016). "Given the DNA methylation profiles of 3 IDH2 mutant gliomas and 41 IDH1 mutant gliomas, we used standard t-tests to identify differentially methylated regions." (PMID 27245697, 2016). "Consistently, inhibition of mutant IDH1 was recently reported to have preclinical efficacy in IDH1 mutant glioma cells and IDH2 mutant AML." (PMID 25825982, 2015). "Negative regulation of IDH2 by miR-183 was suggested in clinical glioma tumor specimens in which IDH2 (mRNA and protein) levels inversely correlated with miR-183 levels." (PMID 26170234, 2015). "Somatic mutations in genes encoding the enzymes IDH1 and IDH2 have been identified through genome-wide sequencing studies in approximately 70% of grade II and III gliomas, and in approximately 5% of GBMs." (PMID 26948489, 2015). "We looked then for association between glioma subtypes (astrocytic, mixed, and oligodendroglial tumors) and IDH1R132H, IDH1nonR132H mutations, and IDH2 mutations." (PMID 24877111, 2014). "Since the OncoPanel sequencing platform includes IDH1 and IDH2, we sought to characterize the spectrum of IDH1/2 mutations given the important clinical and prognostic implications of IDH1/2 mutations in gliomas." (PMID 25257301, 2014). "This metabolite, 2-hydroxyglutaric acid, or 2-HG, has generated a tremendous amount of interest recently because it is also produced in large quantities by the mutant forms of IDH1 and IDH2 that occur in gliomas, acute myeloid leukaemias and other cancers." (PMID 24581008, 2014). "We also strongly recommend the evaluation of IDH1 and IDH2 gene mutations as useful tool for the differential diagnosis between WHO I° LEAT and WHO II° gliomas." (PMID 24858213, 2014). "Complete 1p19q codeletion was found in 150 gliomas: the IDH1 gene was mutated in 137 cases (91.3%) and the IDH2 gene was mutated in 12 of the 13 remaining tumors." (PMID 24877111, 2014). "Frequent mutations in isocitrate dehydrogenase 1 and 2 (IDH1 and IDH2) and the promoter of telomerase reverse transcriptase (TERT) represent two significant discoveries in glioma genomics." (PMID 24722048, 2014). "Surprisingly, 2-HG shows a 100-fold increased concentration in glioma and acute myeloid leukemia's (AML) patients with IDH1 or IDH2 missense mutations." (PMID 25232952, 2014). "At least 8 different mutations of IDH1 and IDH2 are known in gliomas, at the IDH1 R132 and IDH2 R172 loci." (PMID 25376594, 2014). "The accumulation of 2-hydroxyglutarate (2HG) is noted in the cytoplasm of glioma cells with IDH1 mutation and in the mitochondria of cells with IDH2 mutation." (PMID 25376594, 2014).
glioma (continued). "All of the primary gliomas showed consistent IDH1/IDH2 status as the corresponding recurrent gliomas, includingthe three cases of rare mutant (IDH1-R132S, IDH1-R132G and IDH2-R172K)." (PMID 23840696, 2013). "In summary, our study is the first study in investigating the IDH1/IDH2 status in paired primary and recurrent gliomas in Chinese patients." (PMID 23840696, 2013). "A common feature of IDH1 and IDH2 mutations observed in AML and gliomas, however, is the apparent acquisition of enzymatic activity not shared by wild-type enzyme, known as neomorphic activity." (PMID 23847760, 2013). "In our study,we investigated the IDH1 and IDH2 status of 53 pairs of primary and recurrent gliomas by direct sequencing and anti-IDH1-R132H immunohistochemistry." (PMID 23840696, 2013). "Somatic point mutations at hot-spot codons Arg132 (R132) of the IDH1 gene and Arg172 (R172) of the IDH2 genes were identified in 61 of 178 gliomas (34.3%)." (PMID 24083241, 2013). "In conclusion, this study demonstrated a strong tendency of IDH1/IDH2 status being consistent during progression of glioma." (PMID 23840696, 2013). "Excess accumulation of d-2HG has been demonstrated in a subset of cases of glioma and AML with IDH1 or IDH2 mutations." (PMID 23847760, 2013). "Recently, the sequencing of human gliomas has identified mutations in the isocitrate dehydrogenase 1 and 2 (IDH1 and IDH2) genes." (PMID 23894344, 2013). "In support of the results of in vitro enzymatic analyzes, d-2HG levels are 100-fold higher in cases of glioma and AML that carry IDH1 or IDH2 mutations as compared with tumors with wild type IDH." (PMID 23847760, 2013). "The capability of IDH mutations to induce oxidative intracellular conditions is linked to a decrease in GSH levels, observed both in IDH1-R132H—and IDH2-R172K—expressing glioma cells with respect to their wt counterparts." (PMID 22888353, 2012). "IDH2 and IDH1 mutations occur frequently in certain types of World Health Organization grade 2–4 gliomas and in AML cases with a normal karyotype." (PMID 23226729, 2012). "Strikingly, the mutations are single amino acid substitutions at an arginine residue in the active site of the enzyme (e.g., R132 for IDH1 and R172 in IDH2 in gliomas or R140 for IDH2 in AML)." (PMID 23162793, 2012). "The first demonstrations of RCG in cancer cells are consistent with the recent findings that mutant IDH2 in gliomas and AML also produce d-2-hydroxyglutarate from 2OG by “alternate” reduction." (PMID 22675360, 2012). "Within the numbering of the human IDH2 sequence, mutations in Arg172 (an analog of frequently mutated Arg132 of cytosolic IDH1) are detected in gliomas, and mutations in Arg172 and Arg140 (which is adjacent in the active site to Arg172) are found in AML." (PMID 22675360, 2012). "IDH2 is homologous to IDH1, and IDH2 mutations in glioma are specific for R172, the residue that is analogous to IDH1 R132." (PMID 21326614, 2011). "Several different amino acid substitutions recur at either IDH1 R132 or IDH2 R172 in glioma patients." (PMID 21326614, 2011). "Mutations in metabolic enzymes, in particular isocitrate dehydrogenase enzymes (IDH1 and IDH2), have been shown to be involved in glioma development and would facilitate HIF-1 protein stabilization." (PMID 20735813, 2010). "While there is overwhelming evidence that D-2HG acts as an oncometabolite in cells that express mutant IDH1/IDH2, there is limited evidence indicating that changes in D2hgdh expression or activity drive glioma progression, with only a handful of studies hinting this possibility." (PMID 40236175, 2025). "The reduced fluorescence observed in IDH-mutant gliomas has been associated with the intracellular accumulation of the oncometabolite 2-HG, which is produced as a result of the neomorphic enzymatic activity of mutant IDH1 and IDH2 isoforms." (PMID 41008917, 2025). "In tumors, notably in gliomas, IDH1 and IDH2 are frequently mutated." (PMID 40564198, 2025).
glioma (continued). "While IDH1/IDH2 gliomas could be readily identified with 2-HG23, other types of gliomas might not be diagnosed with MS analysis of a single-compound biomarkers, which also applies for most of the cases for cancer diseases." (PMID 40860133, 2025). "Given these challenges, vorasidenib—a selective inhibitor of mutant IDH1 and IDH2—may represent a promising and potentially transformative adjunct in the surgical management of low-grade gliomas." (PMID 41008917, 2025). "However, gain-of-function mutations in IDH1 or IDH2 convert α-KG into D-2-HG, leading to its pathological accumulation in various cancers such as acute myeloid leukemia (AML), glioma, chondrosarcoma, and cholangiocarcinoma." (PMID 40931345, 2025). "The second is a mutation in the IDH genes, IDH1 or IDH2, which is not specific to particular histopathological glioma subtypes but is linked with cellular metabolism." (PMID 38019450, 2024). "In gliomas, R132H is the most common IDH1 mutation, and R172K is the most common IDH2 mutation." (PMID 38951603, 2024). "However, low-grade gliomas with isocitrate dehydrogenase 1 gene (IDH1) and IDH2 mutations, which transform to malignancy are rarer in pediatrics." (PMID 38368566, 2024). "A significant proportion of gliomas carry mutations in the IDH1 and IDH2 genes." (PMID 38540734, 2024). "Surprisingly, no mutations were detected in Idh1, Idh2 and Braf genes that matched to orthologous hot spot mutations in human gliomas and no mutations were observed in spontaneous gliomas (0/4, data not presented)." (PMID 38232086, 2024). "Certain clinical prognostic factors (such as age, gender, immunohistochemical subtypes, infiltration site, tumor size, EOR, BMI, ADC value, ECOG score, etc.)and biological prognostic factors (such as ki-67, IDH1, IDH2, MGMT, etc.)have been shown to predict the risk of recurrence in glioma patients." (PMID 38967893, 2024). "Mutant IDH1 and IDH2 undergo a conformational change resulting in enzymatic activity which converts α-ketoglutarate to its structural derivative 2-hydroxyglutarate which has been found at high concentrations in mutant gliomas." (PMID 38525424, 2024). "Gliomas can be classified into several molecular subtypes, many of which have a well-defined profile of driver mutations, such as those in the isocitrate dehydrogenase 1 (IDH1) or 2 (IDH2) genes." (PMID 36932446, 2023). "In glioma, the mutations occur at the arginine residue at codon 132 in IDH1 (IDH1R132H) and at codon 140 in IDH2, and since the IDH1R132H alteration accounts for 90% of IDH mutations, immunohistochemistry (IHC) evaluation with an IDH1R132H antibody can cover 90% cases of IDH1/2 mutation." (PMID 37158824, 2023). "Vorasidenib is an oral inhibitor of mutant IDH1 and IDH2 glioma cells, specifically designed for brain penetrance, which showed consistent suppression of D-2-hydroxyglutarate (2-HG), the oncometabolite that drives cell proliferation and favors brain-tumor related epilepsy." (PMID 38273856, 2023). "One pertinent example is the glioma CpG island methylator phenotype (G-CIMP), a pattern of genetic changes that includes MGMT methylation, which is often associated with the presence of IDH1 or IDH2 gene mutations." (PMID 36831683, 2023).
glioma (continued). "Isocitrate dehydrogenase-1 and 2 (IDH1 and IDH2) mutations have been described in several tumors, including gliomas, while in MB are rarely reported and not routinely investigated." (PMID 36941703, 2023). "Both IDH1 and IDH2 are somatically mutated in AML predominantly showing hotspot mutations, colon cancer, glioma, enchondromas, spindle cell hemangiomas, osteosarcoma, glioblastoma, chondrosarcomas, intrahepatic cholangiocarcinoma, prostate cancer, and B-acute lymphoblastic leukemia." (PMID 37371524, 2023). "IDH1 and IDH2 mutations are commonly found in low-grade glioma (70% of WHO grade 2 and 3 astrocytomas and oligodendrogliomas) and secondary GBM (which is developed from lower-grade gliomas)." (PMID 37182181, 2023). "Glioma most commonly contains the IDHR132H point mutation; however, other cancers mainly express other IDH variants, including IDH1R132C and IDH1R132G, but also mutations in IDH2, commonly IDH2R140Q and IDH2R172K." (PMID 37296846, 2023). "Therefore, IDH2 mutation is considered as equivalent to IDH1 mutation and IDH2-mutant gliomas are conventionally analyzed along with IDH1-mutant gliomas." (PMID 38012788, 2023). "Phase I/II trials of enasidenib for other tumor types, such as IDH2‐mutated MDS, glioma, or angioimmunoblastic T‐cell lymphoma with an IDH2 mutation, and advanced hematologic malignancies with an IDH2 mutation, are under evaluation (NCT03744390, NCT02273739, and NCT01915498)." (PMID 36254250, 2022). "Moreover, the vast majority of grade II/III gliomas and secondary glioblastomas (grade IV) are linked to better survival with mutations in IDH1 and IDH2 than wild type." (PMID 36497259, 2022). "IDH2 mutations occur frequently in a variety of tumors, including AML, brain tumors, and glioma." (PMID 36335201, 2022). "Gliomas are known to have recurrent hotspot missense mutations in IDH1 and IDH2." (PMID 35806212, 2022). "P3 showed a pathogenic Arg140Gln variant in the IDH2 gene which, to the best of our knowledge, has never been reported in gliomas." (PMID 35456430, 2022). "In IDH-mutant gliomas, IDH1 and IDH2 mutations have typically shown mutual exclusivity." (PMID 36286062, 2022). "Indeed, even IDH1 and IDH2 gliomas, which are considerably more common than CS, are generally studied together because of their small numbers." (PMID 36042521, 2022). "Isocitrate dehydrogenase 1 (IDH1) and isocitrate dehydrogenase 2 (IDH2) are commonly mutated in most low-grade gliomas and secondary glioblastoma multiforme, and IDH mutation status is a feature of glioma subclassifications in the 2016 World Health Organization classification." (PMID 35501312, 2022). "None of the 47 NF1-associated gliomas in this cohort had IDH1 or IDH2 mutation, EGFR amplification, TERT promoter mutation, or histone H3 p.G34 mutation." (PMID 35945463, 2022). "Gliomas with IDH1 and IDH2 mutations had a better prognosis than wild-type gliomas." (PMID 36561336, 2022). "Interestingly, the recently published CATNON trial found no survival benefit of either concurrent or adjuvant TMZ among patients with IDH1 and IDH2 wildtype high-grade gliomas." (PMID 35804921, 2022). "Among these, AG221 (Enasidenib, CC90007; Agios) reported targeting IDH2 mutations and is currently beneath improvement to treat gliomas, in addition to AG881 (a pan-IDH1/-2 (Agios) inhibitor which is being developed for the administration of gliomas cancers." (PMID 35912242, 2022).